RYR1 (ryanodine receptor 1)
Diseases named in the same sentence as RYR1 in open-access papers (continued):
Sharing a sentence is not in itself a finding about the gene and the disease.
Central core disease (continued). "A 14-year-old Chinese boy with a mutation in type 1 Ryanodine receptor (RyR1) whose muscle biopsy diagnosis was central core disease (CCD) had an occurrence of MH after a cervical spine surgery, during which he was placed under general anesthesia without volatile anesthetics or succinylcholine." (PMID 36035384, 2022). "Interestingly, altered ER/SR-mitochondria distance was also reported in RyR1I4895T heterozygous knock-in mice, expressing a mutation orthologous to I4898T in human RyR1 which causes a congenital core myopathy (central core disease)." (PMID 32661288, 2021). "Central Core Disease (CCD) is caused by mutations in the ryanodine receptor 1 gene (RYR1)." (PMID 30804884, 2019). "Among these disorders, central core disease (CCD) is associated with more than 100 RYR1 mutations." (PMID 23308296, 2013). "Based on muscle biopsy’s histological findings, RYR1-RM patients are most commonly classified as having either central core disease (CCD) or multi-minicore disease (MmD)." (PMID 41301517, 2025). "Central core myopathy (CCM) is a rare (prevalence of 1–9 cases per 1,000,000) inherited congenital neuromuscular disorder caused by pathogenic variants to the gene (RYR1) that encodes the ryanodine receptor (RyR1)." (PMID 39108538, 2024). "For example, CNM has been associated with at least seven genes, including MTM1, DNM2, RYR1, TTN, BIN1, CCDC78 and SPEG, whereas RYR1 variations can cause central core disease (CCD), multiminicore disease (MmD), core-rod myopathy, CNM and CFTD." (PMID 35081925, 2022). "On one hand, histological characterization (on muscle biopsy) RYR1-RM collects various nosological entities such as central core disease, multiminicore disease, core–rod myopathy, centronuclear myopathy, and a congenital fiber-type disproportion." (PMID 34827576, 2021). "Histopathological RYR1-RM subtypes include central core disease (CCD), multiminicore disease (MmD), centronuclear myopathy (CNM), core–rod myopathy (CRM), and congenital fiber-type disproportion (CFTD)." (PMID 30406384, 2018). "Main histological subtypes of RYR1-RM include central core disease, multiminicore disease, core–rod myopathy, centronuclear myopathy, and congenital fiber-type disproportion." (PMID 30406384, 2018). "Of these, RYR1-related disorders (RYR1-RD) are the most frequent, identified in 90% of central core disease (CCD) patients, and with a pediatric incidence of at least 1:90,000 within the United States." (PMID 30155738, 2018). "Ca2+ leak through RyR1 has been attributed to hyper-S-nitrosylation in several mouse models of myopathy, including those for muscular dystrophy, central core disease and malignant hypothermia, extreme exercise-induced fatigue, and ventilator-induced diaphragmatic dysfunction." (PMID 38820626, 2024). "In addition, a substitution affecting the corresponding asparagine in RyR1, p.D3330G, has been described in a patient with central core disease (CDD), a neuromuscular disorder." (PMID 34202968, 2021). "Another patient showed composed heterozygosity for both RYR1 and TTN, which supports diagnoses of two NMD, central core disease and limb-girdle dystrophy, respectively." (PMID 37989827, 2024). "However, facial weakness without ophthalmoplegia was described in Central Core Disease, while ophthalmoplegia without facial weakness was reported in RYR1-related centronuclear myopathy." (PMID 35627144, 2022).
centronuclear myopathy (39 papers, 2007 to 2025). Centronuclear myopathy (CNM) is an inherited neuromuscular disorder characterized by clinical features of a congenital myopathy and centrally placed nuclei on muscle biopsy. "Atrial tachycardia and sinus node dysfunction, due presumably to her underlying severe congenital RYR1-associated centronuclear myopathy, were diagnosed." (PMID 31856875, 2019). "She underwent muscle biopsy and genetic analysis that resulted in a diagnosis of severe congenital RYR1-associated centronuclear myopathy." (PMID 31856875, 2019). "An interesting point observed in the case reported by Hayakawa in 2019, of a little girl with a diagnosis of severe congenital RYR1-associated centronuclear myopathy caused by an inherited compound of heterozygous pathogenic/likely pathogenic rare variants in RYR1." (PMID 34827576, 2021). "Mutations in RYR1, known to be associated with core myopathy, seem to be another common cause of centronuclear myopathy and have been described in cases exhibiting variable phenotypes, which generally include a neonatal onset with joint contractures and axial hypotonia." (PMID 29141652, 2017). "Mutations in RYR1 have been associated with centronuclear myopathies and CFTD, and also linked to a susceptibility to malignant hyperthermia (MH), a rare but major complication of anesthesia that manifests itself through a lethal rise in body temperature and tetanic muscle contractions." (PMID 29141652, 2017). "Abnormal triad structure and reduced DHPR and RyR1 expression are features also found in myotubular myopathy patients." (PMID 34768808, 2021). "Other RYR1-related phenotypes with both autosomal dominant and recessive inheritance pattern include multiminicore disease (MnD), centronuclear myopathy (CNM), congenital fiber type disproportion (CFTD), and King-Denborough syndrome (KDS)." (PMID 33170376, 2021). "Both MH and porcine stress syndrome are associated with RYR1 mutations, as are the human muscle disorders, central core disease (CCD), multiminicore disease (MmD), certain nemaline rod-associated myopathies and some centronuclear myopathies." (PMID 25148524, 2014). "This increased expression of SAR1A is specific to KLHL40-deficient skeletal muscle as analysis of skeletal muscle from centronuclear myopathy patients (RYR1 or MTM1 disease-causing mutations) showed no changes in the SAR1A protein levels compared to the control." (PMID 37432316, 2023). "Classical centronuclear myopathies in humans have been associated with dominant mutations in the large GTPase DNM2 gene while recessive cases may be due to mutations of amphiphysin 2, encoded by BIN1, and of the ryanodine receptor (RyR1) gene, RYR1." (PMID 25664165, 2015). "Some of the genes involved in centronuclear myopathies (BIN1 and RYR1) also exhibit alternative splicing defects in the skeletal muscles of individuals affected by DM1." (PMID 41303468, 2025).
rhabdomyolysis (29 papers, 2015 to 2025). Necrosis or disintegration of skeletal muscle often followed by myoglobinuria. "The following list represents rare genetic disorders that commonly afflict pediatric patients and result in rhabdomyolysis: McArdle disease, aldolase A deficiency; disorders of intramuscular calcium release; and ryanodine receptor 1 deficiency." (PMID 39659318, 2024). "Patients with RYR1 variants resulting in malignant hyperthermia susceptibility and/or exertional rhabdomyolysis frequently report additional neuromuscular symptoms such as myalgia and muscle cramps compared with healthy controls." (PMID 36751502, 2022). "We also included disease controls, namely samples from patients carrying dominant RYR1 mutations associated with exertional rhabdomyolysis/exercise intolerance and foetal muscles." (PMID 36196089, 2022). "Some individuals with MHS variants in RYR1 suffer from myalgia, rhabdomyolysis and muscle cramps, and can experience a life-threatening MH-like response to heat and/or exercise." (PMID 33037202, 2020). "Rare variants in several metabolic myopathy genes including CACNA1S, CPT2, LPIN1, PYGM and RYR1 increase myopathy/rhabdomyolysis risk following statin exposure." (PMID 31861911, 2019). "In three related cases with a rhabdomyolysis clinical phenotype, the same RYR1 variant (p.Asp4505His) affected a currently unresolved region between amino acid residues 4354–4631." (PMID 30155738, 2018). "Pathogenic RYR1 variants are a common etiology for exertional rhabdomyolysis and heat stroke during intense exercise in affected individuals, thus impaired bioenergetics along with exercise intensity and environmental factors are important considerations for exercise in this population." (PMID 40993798, 2025). "Interestingly, a link between RYR1 variants, exercise-induced rhabdomyolysis and a lowered MH threshold has been recently postulated." (PMID 37204519, 2023). "Pathogenic RYR1 variants can modify the structure and function of RyR1 channels, leading to mild to severe symptoms ranging from global motor delay and proximal muscle weakness to rhabdomyolysis and myopathic facies." (PMID 35628876, 2022). "From a global point of view, muscles from patients with RYR1 mutations associated with rhabdomyolysis were similar to controls, whereas muscles from XL-MTM patients showed the greatest changes in gene expression, affecting almost all of the transcripts and miRNAs investigated." (PMID 36196089, 2022). "Patient 34, who suffered from a severe episode of heat- and exercise-induced rhabdomyolysis with severe encephalomyelopathy, resulting in a permanent spinal cord lesion, had two RYR1 variants on separate alleles [c.2488C > T (p.Arg830Trp),c.10219G > A (p.Ala3407Thr)]." (PMID 30788618, 2019). "Infection may unmask MHS-related RYR1 mutations and may be an underdiagnosed cause of RYR1-related rhabdomyolysis." (PMID 25929793, 2015). "However, RYR1-related (exertional) rhabdomyolysis occurs mainly in individuals with MHS-associated RYR1 mutations who rarely exhibit any muscle weakness, but rather on the contrary, may exhibit muscle hypertrophy and even superior athletic abilities." (PMID 25929793, 2015). "Cerivastatin was removed from the market due to rhabdomyolysis that resulted in 52 deaths and therefore provides an excellent vehicle to understand the effects of statins on RyR1 channels." (PMID 35703154, 2022). "None of the transcripts examined encoding proteins involved in ECC and calcium homeostasis varied between muscles from healthy controls and disease controls, i.e. patients with RYR1-related rhabdomyolysis/exercise intolerance." (PMID 36196089, 2022). "Human RYR1 mutations that underlie MHS are also frequently associated with heat and/or exercise-induced rhabdomyolysis, exercise intolerance, heat-induced muscle cramps, and death." (PMID 33037202, 2020).
rhabdomyolysis (continued). "There are various triggers for RYR1-related rhabdomyolysis, with exercise being the most important, especially if unaccustomed and performed under extreme environmental circumstances, such as infection and fever." (PMID 32456280, 2020). "Finally, three individuals with RYR1-related exertional rhabdomyolysis were included in the dominant cases." (PMID 40993798, 2025). "The phenotypic trajectory of RYR1-related exertional rhabdomyolysis includes progressive muscle weakness with age, and while this group is affected to a lesser extent vs. CMyo phenotypes, they still report greater fatigue and functional difficulties compared to otherwise healthy individuals." (PMID 40993798, 2025). "However, recent studies have highlighted a potential link between RYR1 mutations and CKD, particularly in individuals experiencing recurrent exertional rhabdomyolysis (ER)." (PMID 40429823, 2025). "Besides these myopathy‐linked PTMs, we also found one phosphorylation, Tyr1375‐P, that was on the β/slow MyHC of all the RYR1 patients (myopathic individuals and those suffering from exertional rhabdomyolysis/myalgia syndrome)." (PMID 37602753, 2023). "MHS has been associated with exercise-induced rhabdomyolysis, and recently, RYR1 mutations have emerged as an important cause, of rhabdomyolysis in healthy persons, even without an association with MHS." (PMID 32456280, 2020). "Moreover, RYR1 SVs, associated or possibly associated with MHS status, have been identified in patients who experienced exertional or stress-induced rhabdomyolysis, which are events similar to those occurring in MHS patients after exposure to anesthetics." (PMID 31165076, 2019). "The histopathological features of malignant hyperthermia (MH) and non-anaesthetic (mostly exertional) rhabdomyolysis (RM) due to RYR1 mutations have only been reported in a few cases." (PMID 30788618, 2019). "Myalgia or cramp was a universal feature, indicating overlap with the spectrum of RYR1-related exertional myalgia/rhabdomyolysis, and this, together with the later age at onset, may be a phenotypic clue for future cases." (PMID 29298851, 2018). "The ability of simvastatin to activate RyR1 may be common to other statins and could explain why cerivastatin, a compound removed from the market due to reports of rhabdomyolysis, was shown to trigger Ca2+ release from isolated skeletal SR vesicles." (PMID 29278865, 2018). "Enhanced sarcoplasmic reticulum calcium stores and post-translational modulation of RYR1 calcium release by oxidation (S-nitrosylation) or beta-adrenergic-induced phosphorylation are potential mechanisms that could enhance RYR1 calcium release and trigger an episode of rhabdomyolysis." (PMID 36292738, 2022). "Importantly, muscles from patients carrying dominant RYR1 mutations linked to rhabdomyolysis did not exhibit any changes in the expression of the investigated transcripts." (PMID 36196089, 2022). "Two RYR1 variants were reported: (a) R2454G associated with fulfilment malignant hyperthermia and a high affinity for ryanodine binding and (b) C7360G associated with both anesthetic-induced malignant hyperthermia and exertional/non-exertional rhabdomyolysis." (PMID 32381029, 2020). "Similar to gene expression results, muscles from disease controls, i.e. patients with RYR1-related rhabdomyolysis/exercise intolerance showed no changes in expression of any of the investigated miRNAs." (PMID 36196089, 2022). "As our LC/MS analysis revealed that Tyr1375‐P was not specific to myopathic patients and was also present in patients with RYR1‐related rhabdomyolysis/myalgia and no muscle weakness, we anticipated stronger changes in myosin rod structure and dynamics for Ser1362‐P." (PMID 37602753, 2023).
muscular dystrophies (22 papers, 2012 to 2025). "Another differential diagnosis is neuromuscular disorders, including muscular dystrophy, inflammatory myopathies, and malignant-hyperthermia susceptibility (e.g., RYR1 mutation)." (PMID 39463617, 2024). "RyR1 oxidation has been linked to SR Ca2+ leak and impaired muscle function during extreme exercise and in heart failure and muscular dystrophies." (PMID 35506650, 2022). "For example, we identified compound heterozygous mutations (including a nonsense mutation) in the ryanodine receptor (RYR1) in patient P presenting with muscular dystrophy and arthrogryposis." (PMID 22526018, 2012). "In skeletal muscle, RyR1 leak contributes to muscle weakness in inherited myopathies, to age-related loss of muscle function and cancer-associated muscle weakness, and to impaired muscle function in muscular dystrophies, including Duchenne." (PMID 36647824, 2023). "Our data suggest that leaky RyR1 channels may underlie multiple forms of muscular dystrophy linked to mutations in genes encoding components of the dystrophin-glycoprotein complex." (PMID 22640601, 2012). "Congenital myopathies and muscular dystrophies yielded a comparable ‘solved’ rate of 53%, spanning 16 genes, including known variants in STAC3, RYR1 and COL6A2/3 in addition to 21 novel variants across 14 genes." (PMID 37516995, 2023). "Our group has reported similar remodeling of RyR1 in skeletal muscle from aged mice and in murine models of muscular dystrophies, all of which exhibit intracellular Ca2+ leak and reduced muscle specific force production." (PMID 35506650, 2022). "The pathophysiological similarities between the two types of muscular dystrophy, which both result from disruption of the DGC, suggest that RyR1-mediated SR Ca2+ leak is a common mechanism for DGC-related muscular dystrophy." (PMID 22640601, 2012). "Rhabdomyosarcomas have been described in association with thyroid disease, dermatomyositis, Duchenne muscular dystrophy, and in muscular dystrophy models but not in patients with ryanodine receptor-1 gene (RYR1) pathogenic variants." (PMID 37510264, 2023). "Further, several experiments indicate a relationship between muscle weakness and nitrosylation of RYR1 in muscular dystrophies and in the heart stressing the importance of a tightly controlled NO production to maintain calcium homeostasis and correct muscle function." (PMID 25853139, 2015). "Rhabdomyosarcomas have been described in association with concomitant thyroid disease, dermatomyositis, Duchenne muscular dystrophy, and muscular dystrophy animal models, but have never been reported as associated with ryanodine receptor 1 gene (RYR1) pathogenic variants." (PMID 37510264, 2023). "It is unknown whether RyR1 dysfunction occurs also in other muscular dystrophies." (PMID 22640601, 2012). "Even though it has been shown previously that RyR1 is leaky in dystrophic muscle and contributes to the disease phenotype, and drugs that stabilize RyR1 are known to be effective in muscular dystrophy 23, we could not see a similar effect with Dantrolene in this experiment." (PMID 24270550, 2013).